KRAS (KRas proto-oncogene, GTPase)
Diseases named in the same sentence as KRAS in open-access papers (continued):
Sharing a sentence is not in itself a finding about the gene and the disease.
lung adenocarcinoma (continued). "In conclusion, using a molecular morphometric approach we were able to demonstrate sub-clonality for KRAS and EGFR mutations in lung adenocarcinoma." (PMID 28501852, 2017). "Codons 12, 13, or 61 are typically mutated in KRAS; similar mutations affect homologous genes HRAS and NRAS, though infrequently for lung adenocarcinomas." (PMID 29322935, 2017). "The TMA slides, obtained from the University of Pittsburgh Lung Specialized Program of Research Excellence (SPORE) and constructed using randomly selected archival lung adenocarcinomas with known EGFR and KRAS mutation status, were stained for MAP4K4." (PMID 28306189, 2017). "Using molecular and morphometric approach, 347 lung adenocarcinoma samples were analyzed for KRAS and EGFR sub-clonality, which was further correlated with clinical and pathological variables." (PMID 28501852, 2017). "Alexander reported that patients with malignant pleural effusion of lung adenocarcinoma had increased frequency of EGFR and KRAS mutations." (PMID 28938549, 2017). "Here, we found a greater proportion of KRAS mutation subgroup showed the higher expression of PD-L1, compared with that of EGFR/ALK/KRAS wild-type subgroup in lung adenocarcinoma patients." (PMID 28451792, 2017). "In previous work, we generated a new class of drug leads called lipophilic bisphosphonates for the treatment of both KRAS-driven lung adenocarcinomas and malaria." (PMID 29118758, 2017). "For decades, mutations in KRAS and EGFR have been recognized to play a critical role in lung adenocarcinoma and have been used to classify these tumors into subtypes based on mutation status." (PMID 29322935, 2017). "Among the three groups, we evaluated only patients with stage IIIB–IV lung adenocarcinoma who had EGFR mutations (n = 126), KRAS mutations (n = 35), or ALK rearrangements (n = 47)." (PMID 27518729, 2016). "Several components of the Raf/MAPK pathway show strong selective activation in KRAS-mutant lung adenocarcinomas, providing further corroboration that this pathway is a key therapeutic target for KRAS-mutant lung tumors." (PMID 27301828, 2016). "The aim of this study was to present the EGFR, KRAS and ALK mutations in a representative cohort of patients with lung adenocarcinomas in Croatia and to correlate the mutational status with clinical data." (PMID 27655296, 2016). "Two STAT3 siRNAs decreased PD-L1 expression by 10–32% in two of the three KRAS-mutant lung adenocarcinoma cell lines (p < 0.05), while the PI3K inhibitor LY294002 (40 μM) did not change the expression level." (PMID 27846317, 2016). "Activation of KRAS promotes the growth and progression in various malignancies, including lung adenocarcinoma, mucinous adenoma, ductal carcinoma of the pancreas and CRC." (PMID 27769041, 2016). "The frequency of these driver mutations were identical to the previous report that analyzed unselected Japanese lung adenocarcinoma patients; EGFR mutation, KRAS mutation, ALK fusion, or HER2 mutation were identified in 67.7% (216/319)." (PMID 27100677, 2016). "To support the specificity of the MAPK signal for PD-L1 regulation, we subjected the three KRAS-mutant lung adenocarcinoma cell lines to PMA stimulation in order to directly activate ERKs, which was associated with a significant increase in PD-L1 mRNA levels." (PMID 27846317, 2016). "The study assessing molecular characteristics of lung adenocarcinomas, which harbor EGFR, KRAS mutations or ALK rearrangements as well as triple negative adenocarcinomas, dominated the top 10 alignment outcomes." (PMID 26967245, 2016).
lung adenocarcinoma (continued). "Among the three groups, we evaluated only patients with stage IIIB–IV lung adenocarcinoma who had EGFR mutations (n = 126), KRAS mutations (n = 35), or ALK rearrangements (n = 47) to avoid the influence of confounding factors such as tissue type and staging." (PMID 27518729, 2016). "Serial plasma samples from lung adenocarcinoma patients treated with TKIs were used to quantify EGFR and KRAS mutations in circulating DNA by digital PCR." (PMID 27640882, 2016). "We found that OTUB1 up‐regulation contributes specifically to the development of wt KRAS lung adenocarcinomas by inhibiting reversible ubiquitination of RAS proteins." (PMID 26881969, 2016). "Many studies in human lung adenocarcinoma patients showed that KRAS and EGFR mutations are mutually exclusive and KRAS confers resistance to treatment with EGFR TKIs." (PMID 27458163, 2016). "Analysis of a well-validated mouse model of KRAS-mutant lung adenocarcinoma revealed that tumors showed significant activation of NF-κb and furthermore that these tumors were dependent upon NF-κb activity for tumor maintenance." (PMID 27301828, 2016). "We also observed a higher proportion of wt KRAS lung adenocarcinomas with medium/high levels of OTUB1 expression compared to mutant KRAS tumors." (PMID 26881969, 2016). "Of particular importance, the system reported similar expression patterns for primary tumor samples from patients with lung adenocarcinoma (positions 1-10) with ranking attributed to the mutation pattern either in EGFR, KRAS, or ALK genes." (PMID 26967245, 2016). "In summary, our findings demonstrated that lung adenocarcinoma with clear cell component is a rare, malignant tumor with poor prognosis and displays more frequent EGFR and KRAS mutations." (PMID 27013585, 2016). "Here we examined protein and gene expression from the Cancer Genome and Proteome Atlases (TCGA and TCPA) to characterize proteins and protein-coding genes that are selectively upregulated in KRAS-mutant lung adenocarcinomas." (PMID 27301828, 2016). "Three KRAS-mutant lung adenocarcinoma cell lines (NCI-H1373, NCI-H358, and NCI-H441) were evaluated for PD-L1 expression 24 h after treatment with the MEK inhibitor U0126." (PMID 27846317, 2016). "KRAS-mutants were compared to other lung adenocarcinoma samples and were also examined for the effects of commonly co-occurring mutations." (PMID 27301828, 2016). "In this study, we analyzed genomic and proteomic data from human lung adenocarcinomas to examine the strength and variability of mutant-KRAS activation of proteins and genes." (PMID 27301828, 2016). "The main objective of the present study was to analyze the EGFR, KRAS and ALK mutation status in a representative cohort of patients in Croatia with lung adenocarcinomas and to correlate the mutational status with clinical data." (PMID 27655296, 2016). "Here, for the first time, we have presented representative data for Croatian patients with lung adenocarcinomas, and we demonstrate a higher prevalence of the specific L858R mutation in the EGFR gene, as well as a higher prevalence of KRAS mutations." (PMID 27655296, 2016). "In summary, this study showed that PD-L1 expression is regulated by MAPK and partially by STAT3 signaling in KRAS-mutant lung adenocarcinoma cell lines." (PMID 27846317, 2016). "KRAS‐mutant lung adenocarcinomas have higher levels of the MAPK pathway activation than wild‐type (wt) KRAS tumors." (PMID 26881969, 2016). "Collectively, these results suggest that Sirt2 deletion enhances the progression of oncogenic KRAS-induced lung adenocarcinomas." (PMID 27637077, 2016). "We then looked at RNA-seq data to find genes with the greatest induction specifically in KRAS-mutant lung adenocarcinomas." (PMID 27301828, 2016). "We subjected the three KRAS-mutant lung adenocarcinoma cell lines to STAT3 RNAi, and PD-L1 expression decreased in two of them, NCI-H1373 and NCI-H441, but not in NCI-H358 cells, at both protein and mRNA levels." (PMID 27846317, 2016).
lung adenocarcinoma (continued). "In contrast, patients with EGFR-positive lung adenocarcinoma tended to present with GGO, and patients with KRAS-positive lung adenocarcinoma tended to present with a solid tumor that had limited tendency to metastasize to the lung and pleura." (PMID 27518729, 2016). "Next, we compared the expression of RAC2 and CDA mRNAs between DMSO and U0126 treatments in the three KRAS-mutant lung adenocarcinoma cell lines." (PMID 27846317, 2016). "Lung adenocarcinoma with clear cell component is a rare, malignant tumor with poor prognosis and displays more frequent EGFR and KRAS mutations." (PMID 27013585, 2016). "Here we demonstrate that STAT3 plays an unexpected tumour-suppressive role in KRAS mutant lung adenocarcinoma (AC)." (PMID 25734337, 2015). "The IASLC/ATS/ERS lung adenocarcinoma classification system has powerful prognostic value and shows molecular correlations (such as thyroid transcription factor-1, Ki-67, EGFR/KRAS mutations)." (PMID 26318038, 2015). "To date, the EGFR and KRAS gene mutations, and the EML4-ALK fusion gene have been identified as major oncogenic driver mutations of lung adenocarcinomas." (PMID 26268359, 2015). "LDHB is associated with glycolytic phenotypes in triple-negative breast cancer and KRAS-dependent lung adenocarcinomas, in which LDHB is the predominant form for glycolysis." (PMID 25973606, 2015). "Current international guidelines recommend analysis of the following seven genes before starting palliative intent therapy for lung adenocarcinoma: KRAS, EGFR, ALK, ROS1, HER2, BRAF, RET." (PMID 26018876, 2015). "The poor survival of KRAS mutants is partly explained by enrichment of lung adenocarcinoma in these groups." (PMID 26278961, 2015). "Our results provide strong rationale to explore anti-mesothelin targeted therapies in advanced lung adenocarcinoma especially in the KRAS-mutant subgroup." (PMID 26028668, 2015). "This study explored the activated and interconnected signaling network of KRAS mutant lung adenocarcinomas (AD) to identify novel therapeutic targets." (PMID 26468985, 2015). "The predictive role of KRAS is controversial, with prior studies of KRAS MT in lung adenocarcinoma yielding contradictory conclusions." (PMID 26471290, 2015). "Our group recently reported the use of a novel hybrid nanoparticle delivery system for the efficient and safe delivery of siRNA against mutant KRAS in A549 lung adenocarcinoma cells." (PMID 26410728, 2015). "For example, LDHB is overexpressed and required for the growth of KRAS-dependent lung adenocarcinomas." (PMID 26426634, 2015). "‘Exclusivity plots’ for COAD revealed mutations in BRAF to be negatively associated with mutations in KRAS, to a degree similar to that we observed for co-existing mutations of EGFR and KRAS in lung adenocarcinoma." (PMID 26047463, 2015). "We detected the KRAS and EGFR mutation as well as the KIF5B-RET fusion gene in primary lung adenocarcinomas." (PMID 26268359, 2015). "RFS of lung adenocarcinoma patients harboring EGFR mutations, KRAS mutations or ALK fusions were compared to that of wild-type patients." (PMID 26486077, 2015). "KRAS-driven lung adenocarcinomas with wild-type LKB1 are more sensitive to bromodomain inhibitor JQ1 than those with alterations in LKB1." (PMID 26485762, 2015). "Lung adenocarcinomas have mutually exclusive mutations in receptor tyrosine kinase (RTK) and RAS pathway oncogenes such as EGFR and KRAS." (PMID 26544513, 2015).
lung adenocarcinoma (continued). "In support of such an idea, studies from several groups have shown that NOTCH1 is required for lung tumorigenesis in genetically engineered mouse models of lung adenocarcinoma that commonly express mutant KRAS." (PMID 26491213, 2015). "In our study we used 2 genetically dissimilar human lung adenocarcinoma cell lines: EGFR mutant (exon 21 L858R mutation) T2851 cells and T2821 cells expressing wild type (wt) KRAS and EGFR." (PMID 26517240, 2015). "We analyzed whole exome sequencing data from 16 EGFR/KRAS/ALK-negative lung adenocarcinomas and additional 54 tumors in two expansion cohort sets." (PMID 24576404, 2014). "A considerable proportion of lung adenocarcinomas develop through acquisition of mutations in EGFR, KRAS, or ALK genes." (PMID 24466154, 2014). "Multiple activating mutations in oncogenes have been found in lung adenocarcinomas, including in the following genes: EGFR (39%), KRAS (20%), ALK fusions (notably with EML4) (4%), ERBB2 (3%) and BRAF (3%), which are found to be mutually exclusive." (PMID 24489653, 2014). "Here, we describe the role of ACK1, a non-receptor tyrosine kinase in abrogating migration and invasion in KRAS mutant lung adenocarcinoma." (PMID 24461128, 2014). "Our data suggests that KRAS is amplified in ovarian, gastric, lung adenocarcinoma, and uterine cancers, with a copy number range 10–40 in ovarian cancers." (PMID 24874471, 2014). "A previous study indicated that the most frequent gene alteration in lung adenocarcinomas in Japanese patients is the EGFR mutation, with an incidence of 38%, while the most frequent gene alteration in Caucasians is KRAS mutation, with an incidence of 30%." (PMID 25364428, 2014). "In conclusion, our work illustrated the mutation spectrum of EGFR, KRAS, HER2, BRAF and ALK in lung adenocarcinoma, as well as confirmed that hTERT 5′ promoter region mutation rarely occurred in NSCLC samples." (PMID 25198510, 2014). "We have screened the prevalence of known driver mutations of EGFR, KRAS, HER2, BRAF and ALK in a cohort of 107 lung adenocarcinoma sample with complete prognostic information." (PMID 25198510, 2014). "We identified several targetable pathways in EGFR/KRAS/ALK-negative lung adenocarcinoma including PI3K/mTOR signaling (TSC1, PIK3CA, AKT2), receptor tyrosine kinase signaling (ERBB4), cell cycle regulation (CHEK2, CDC27), and DNA repair (PARP4)." (PMID 24576404, 2014). "EGFR, KRAS, HER2, BRAF mutation and ALK fusion were mutated in 25.2%, 6.5%, 1.9%, 0.9% and 3.7% of lung adenocarcinomas." (PMID 25198510, 2014). "Because mutations of EGFR, KRAS, HER2, BRAF, as well as ALK fusions have been well established to be existed in lung adenocarcinoma, these mutation and fusion genes that ‘drives’ lung adenocarcinoma were not screened in lung squamous cell carcinoma." (PMID 25198510, 2014). "According to specific oncogenic driver mutations, lung adenocarcinoma is divided to molecular subtypes such as EGFR, KRAS, ALK, HER2, BRAF and so on." (PMID 25198510, 2014). "The most diffused currently in use are tyrosin kinase inhibitors for EGFR-mutated lung adenocarcinomas, trastuzumab for HER2-negative breast cancer and cetuximab or panituximab for KRAS-mutated CRC." (PMID 25202344, 2014). "Recent sequencing data shows that RASA1 mutations are observed in lung adenocarcinoma (COSMIC database), so further effort should be directed towards understanding the relationship between RASA1, DOK2, EGFR, and KRAS in lung adenocarcinoma." (PMID 24255704, 2013). "We provide a comprehensive overview of the genomic and transcriptional landscape in lung adenocarcinoma stratified by EGFR and KRAS mutations." (PMID 24205279, 2013). "In the current study we delineate genomic and transcriptional alterations in lung adenocarcinoma stratified by EGFR and KRAS mutation status." (PMID 24205279, 2013).
lung adenocarcinoma (continued). "Together, our results suggest that the genomic and transcriptional landscape of lung adenocarcinoma is only to a minor extent determined by the mutational status of EGFR and KRAS." (PMID 24205279, 2013). "Most activating KRAS mutations in NSCLC are located in codons 12 or 13, and are also reported in lung adenocarcinomas." (PMID 27234388, 2013). "For lung adenocarcinoma, EGFR mutation and ALK rearrangement testing is recommended, KRAS mutation testing is suggested by the NCCN guidelines." (PMID 27605195, 2013). "Our analyses suggest that the overall genomic and transcriptional landscape of lung adenocarcinoma is affected, but only to a minor extent, by EGFR and KRAS mutation status." (PMID 24205279, 2013). "KRAS mutant lung adenocarcinomas are generally refractory to conventional cytotoxic therapies and currently available small molecule targeted agents." (PMID 22654667, 2012). "Major recurrent mutations in lung adenocarcinoma have been found to occur in EGFR, KRAS, HER2, BRAF, ALK and ROS1." (PMID 22140546, 2011). "Support for a developmental sequence from AAH to adenocarcinoma also comes from conditional oncogenic mouse models for lung adenocarcinoma, in which KRAS or EGFR genes are activated." (PMID 21731750, 2011). "LOH events at 9q and 16p, key features of lung cancer, have been reported to occur at similar frequencies in AAH and adenocarcinoma, and the mutually exclusive natures of KRAS and EGFR mutations reported in lung adenocarcinoma are maintained in AAH lesions." (PMID 21731750, 2011). "In this study we also assessed EBUS-derived needle aspirates for KRAS mutations using COLD-PCR and found these in 19% of lung adenocarcinomas and 27.7% of NSCLC-NOS." (PMID 21949883, 2011). "We then evaluated the effect of KRAS alterations on clinical outcome of 237 resected lung adenocarcinoma tumors which were limited to stage I–III cases with survival data." (PMID 19826477, 2009). "Lung adenocarcinomas also harbor activating mutations in the downstream GTPase, KRAS, and mutations in EGFR and KRAS appear to be mutually exclusive." (PMID 15696205, 2005). "KRAS G12D has been reported in approximately 20% of lung adenocarcinoma cases." (PMID 39852181, 2025). "Here, we report that chronic exposure to diesel exhaust particles (DEPs), a major component of PM2.5, induces an immunosuppressive lung microenvironment that promotes tumour progression in a KRAS-driven lung adenocarcinoma model (KrasLSL-G12D/+-Trp53lox/lox or KP mice)." (PMID 41274118, 2025). "In addition, another novel SLC7A11 inhibitor, HG106, exhibited specific cytotoxicity against KRAS-mutant lung adenocarcinoma cells by inducing cell apoptosis through enhanced oxidative stress and ER stress pathways." (PMID 39569390, 2025). "IgA and IgG expression in tumors have shown predictive value in melanoma and KRAS-mutated, but not KRAS wild-type, lung adenocarcinoma (LUAD)." (PMID 40990023, 2025). "Mutant KRAS-driven lung adenocarcinoma presents a serious challenge in oncological clinic." (PMID 39979425, 2025). "Lung adenocarcinomas driven by KRAS oncogenes are among the most severe and lethal types of cancer." (PMID 41219537, 2025). "To demonstrate the versatility and scalability of Metient, we applied it to a KRAS-mutant lung adenocarcinoma cell line with single-cell lineage tracing, a domain where migration history reconstruction was previously constrained by only simplified models of metastatic spread." (PMID 39282311, 2025).